INS (insulin)
Diseases named in the same sentence as INS in open-access papers (continued):
Sharing a sentence is not in itself a finding about the gene and the disease.
type 1 diabetes (continued). "In the EASE (Empagliflozin as Adjunctive to inSulin thErapy) trials, empagliflozin at 10 and 25 mg, as well as a unique dose of 2.5 mg, in addition to intensive insulin therapy in people with type 1 diabetes was evaluated." (PMID 39598003, 2024). "For example, children with type 1 diabetes should be able to use insulin regularly, exercise, maintain a healthy diet, and be aware of the signs of hypoglycemia." (PMID 39158952, 2024). "In type 1 diabetes, hypoglycaemia is common as it is an autoimmune disease in which the immune system attacks and destroys the insulin‐producing beta cells in the pancreas." (PMID 39238070, 2024). "In this study, we conducted 20 interviews with adolescents and young adults (AYAs) with Type 1 Diabetes using hybrid closed-loop insulin pump systems for self-management routines." (PMID 38846748, 2024). "In individuals with long-standing type 1 diabetes (medalists, over 50 years), residual C-peptide secretion and insulin-positive beta cells are still detectable." (PMID 38864887, 2024). "Type 1 diabetes mellitus (T1DM), also known as insulin-dependent diabetes, is characterized by an autoimmune reaction leading to the destruction of pancreatic beta cells, usually resulting in total insulin secretion loss." (PMID 39720174, 2024). "Continuous subcutaneous insulin infusion (CSII), also known as insulin pump therapy, has a clear place in the management of type 1 diabetes." (PMID 38951212, 2024). "Accurate prediction of blood glucose levels is essential for type 1 diabetes optimizing insulin therapy and minimizing complications in patients with type 1 diabetes." (PMID 38354168, 2024). "ORs were expressed per 1 SD intake of nutrient and were adjusted for other macronutrient intakes, age, sex, socioeconomic status, BMI, duration of type 1 diabetes, pump use, insulin dose and alcohol intake." (PMID 38967668, 2024). "Previous studies have revealed heterogeneity in the progression to clinical type 1 diabetes in children who develop islet-specific antibodies either to insulin (IAA) or glutamic acid decarboxylase (GADA) as the first autoantibodies." (PMID 38714671, 2024). "The Automated insulin Delivery Amongst Pregnant women with Type 1 diabetes (AiDAPT) trial provided landmark evidence supporting use of a uniquely adaptive HCL system (CamAPS FX) across a generalisable patient population." (PMID 38967667, 2024). "The diabetic mice were insulin-treated, as are humans with Type 1 diabetes, avoiding the potential confounder of non-insulin treatment." (PMID 38397785, 2024). "Barriers to Uptake of Open-Source Automated Insulin Delivery Systems: Analysis of Socioeconomic Factors and Perceived Challenges of Caregivers of Children and Adolescents With Type 1 Diabetes From the OPEN Survey." (PMID 39196351, 2024). "An insulin pump equipped with AI for type 1 diabetes can autonomously adjust insulin delivery based on real-time glucose data and predictive algorithms." (PMID 39336497, 2024). "Type 1 diabetes (T1D) is a chronic condition characterized by a deficit in insulin secretion secondary to immune-mediated damage to pancreatic beta cells." (PMID 38538781, 2024). "CD8+ T cells destroy insulin-producing pancreatic β cells in type 1 diabetes through HLA class I–restricted presentation of self-antigens." (PMID 39286976, 2024). "Here, we present a case of chronic spontaneous urticaria in a 9-year-old with type 1 diabetes and autoimmune thyroid disease who first presented with insulin pump site reactions concerning an insulin-related allergy." (PMID 38655126, 2024). "This study demonstrates that an RL algorithm can be employed to provide personalized insulin doses, ensuring sufficient glycemic control in patients with type 1 diabetes." (PMID 37971630, 2024). "In dysregulated states such as type I diabetes, INS signaling is impaired, leading to disrupted glucose metabolism and glycogenesis." (PMID 39769264, 2024).
type 1 diabetes (continued). "Intensive insulin therapy can significantly slow the progression of this marker in patients with type 1 diabetes, indicating a potential protective effect against atherosclerosis." (PMID 39125938, 2024). "Current methods of blood glucose management in type 1 diabetes rely on regular self-monitoring of blood glucose levels and insulin administration." (PMID 39335656, 2024). "Clinical studies establishing the effect of insulin treatment and modification of vascular complications with respect to age of type 1 diabetes diagnosis and duration of disease would provide insights into the skeletal benefits beyond glycaemia." (PMID 38761257, 2024). "PSE was shown to be effective in promoting insulin sensitivity, decreasing inflammation, and lowering blood glucose levels in a type 1 diabetes mouse model." (PMID 39683552, 2024). "This is crucial as there is a dearth of data on the efficacy and safety of virtual insulin pump initiation in children with type 1 diabetes." (PMID 38745900, 2024). "Patients with type 1 diabetes rely on various insulin delivery methods, such as insulin pens, insulin pumps, or hybrid closed-loop systems, which require substantial use interaction." (PMID 39091290, 2024). "Recent research in cell replacement strategies for treating type 1 diabetes has expanded beyond auto-, allo-, and xenotransplantation to include the differentiation of induced pluripotent stem cells into insulin-producing β-cells for transplantation." (PMID 39560873, 2024). "Type 1 diabetes (T1D) is an autoimmune disease that attacks the cells of the pancreas responsible for producing insulin." (PMID 39652222, 2024). "The most widely used model is the streptozotocin (STZ) rat, in which Type 1 diabetes is induced by chemically destroying the insulin-secreting pancreatic β cells." (PMID 39201727, 2024). "DNA origami-integrated insulin nanorods stimulated glucose uptake along with desired response in type I diabetes-prompted zebrafish model." (PMID 39771551, 2024). "Estimated glucose disposal rate (eGDR) is a validated tool to estimate insulin sensitivity in type 1 diabetes using HbA1c, waist circumference, and presence of hypertension." (PMID 39906033, 2024). "Existing type 1 diabetes (T1D) simulators employ physiological models of the glucose-insulin system for the purpose of synthesizing glycaemic scenarios emulating real-life T1D patients." (PMID 38493243, 2024). "Administration of Insulin-MHC-Fc to type 1 diabetes patients is expected to coat insulin-reactive CD4+ T cells via T cell receptor-MHC interaction." (PMID 38097717, 2024). "In type 1 diabetes, one study showed that 7 years of intensive insulin therapy improved BMD and decreased bone resorption markers." (PMID 38761257, 2024). "We evaluate the energy and nutrient intake of children, adolescents, and young adults with type 1 diabetes (T1D) who started to use automated insulin delivery (AID) systems before the transition and during follow-up for 6 months in a real-world setting." (PMID 38459160, 2024). "Short peptides of less than eight amino acids were used in a study to treat mice with type I diabetes and were found to control insulin levels and restore blood sugar levels." (PMID 39594008, 2024). "In this report, we present the case of a diagnosis of HNF1A MODY in a black sub-Saharan African young adult previously diagnosed with type 1 diabetes and treated with multiple daily insulin injections." (PMID 39420387, 2024). "Worldwide, nearly 9 million people are living with type 1 diabetes (T1D), an autoimmune disease that requires lifelong treatment with exogenous insulin." (PMID 39703363, 2024). "Under clamped conditions, the insulin concentration was more than twice as high in the group with type 2 compared to the group with type 1 diabetes." (PMID 38376580, 2024). "The efficacy of the newly synthesized insulin derivative FHI was also screened in vivo in a Streptozotocin (STZ) induced Type I diabetes mouse model." (PMID 39043846, 2024).
type 1 diabetes (continued). "Daily insulin doses and sensor data of children and adolescents with type 1 diabetes using the advanced hybrid closed-loop system at the initiation of the system and after 6, 12, and 24 months of follow-up." (PMID 38390211, 2024). "On the other hand, hypoglycemia as a complication of type I diabetes treatment can be averted by meticulous measuring plasma glucose concentration and through the precise adjustment of insulin doses." (PMID 39062768, 2024). "Type 1 diabetes mellitus is a chronic disease characterized by insufficient insulin production following autoimmune destruction of pancreatic β-cells, leading to hyperglycemia." (PMID 38474380, 2024). "Type 1 diabetes (T1D) is an autoimmune disease characterized by the destruction of insulin-producing β-cells in the pancreas." (PMID 39411715, 2024). "Type 1 Diabetes (T1D) is a chronic autoimmune disease that results from the destruction of β cells in the pancreas, leading to an inability to secrete insulin and regulate blood glucose levels." (PMID 39766858, 2024). "Golimumab treatment promoted endogenous insulin production in children and adolescents with newly diagnosed type 1 diabetes, while the need for exogenous insulin declined." (PMID 38776022, 2024). "Although this condition is usually managed through the administration of exogenous insulin, one therapeutic option for patients suffering from type 1 diabetes is allogenic islet transplantation to replace the β-cell mass lost to autoimmune destruction." (PMID 38474380, 2024). "In complementary experiments, mice were injected with streptozotocin (STZ), an alkylating agent that disrupts β cell in the pancreas, impairs insulin production, and induces type 1 diabetes in mice." (PMID 38820148, 2024). "Type 1 diabetes mellitus (T1DM) is an endocrine disease caused by the combined action of susceptibility genes and environmental factors, leading to destruction of β cells and a lifelong dependence on insulin therapy." (PMID 39957850, 2024). "In this study, the titer of insulin antibodies was comprehensively measured in patients with type 1 diabetes treated via insulin injection therapy and still had a clinically high GV." (PMID 38541176, 2024). "The INHALE-3 study is a Phase 4 randomized controlled trial evaluating the efficacy and safety of inhaled insulin Afrezza combined with insulin Degludec (Novo Nordisk, Bagsværd, Denmark) versus usual care in adults with Type I diabetes." (PMID 39006724, 2024). "Type 1 diabetes is characterised by the invasion of the islets of Langerhans by immune cells and by an autoimmune attack against insulin-secreting beta cells." (PMID 38967669, 2024). "Individuals with Type 1 diabetes can benefit from continuous subcutaneous insulin infusions, oral medication, and a nutritious diet combined with a healthy lifestyle, thyroid dysfunction treatment, and glucose self-monitoring." (PMID 38371502, 2024). "Type 1 diabetes (T1D) represents a significant clinical condition marked by the autoimmune attack of pancreatic beta cells, leading to an insufficiency of insulin secretion." (PMID 39371824, 2024). "Insulin therapy employing an insulin pump was introduced at the end of the 1970s, and in Romania, the use of insulin pumps for patients with type 1 diabetes was introduced in 2002 in Cluj-Napoca." (PMID 39376804, 2024). "The expression of different classes of non-coding RNAs present in insulin-secreting cells is altered during the initial phases of type 1 diabetes and participates in beta cell failure." (PMID 38967669, 2024). "Type 1 diabetes is an autoimmune disease in which the immune system erroneously attacks and destroys the insulin-producing pancreatic β cells." (PMID 38906178, 2024). "Type 1 diabetes was induced via streptozotocin and rescued via subcutaneous semi-osmotic insulin pump for 8 weeks." (PMID 38786744, 2024).
type 1 diabetes (continued). "For insulin pump therapy with CGM to be widely adopted in older patients with type 1 diabetes, it is necessary to develop a simpler insulin pump and to secure human resources and financial support for its management." (PMID 39375857, 2024). "From the introduction of continuous glucose monitoring (CGM) in treatments of type 1 diabetes, particularly its integration with insulin pumps, there has been a quest for new parameters that describe optimal glycemic control." (PMID 38957442, 2024). "Type 1 diabetes (T1D) arises from autoimmune-mediated destruction of insulin-producing pancreatic beta cells." (PMID 38975343, 2024). "Our data point to tRFs as novel players in the crosstalk between the immune system and insulin-secreting cells and suggest a potential involvement of this novel class of non-coding RNAs in type 1 diabetes pathogenesis." (PMID 38967669, 2024). "Early onset, significant insulin shortage, prolonged illness duration, and high rates of neurological and vascular consequences are typical characteristics of type 1 diabetes." (PMID 38398492, 2024). "Studies were included if they reported on achieved insulin independence, involved more than 10 patients with type 1 diabetes, and had a mean follow-up period of at least one year." (PMID 39767759, 2024). "AI has also been applied in type 1 diabetes, for instance in optimising insulin pump settings, in potentially identifying predictive biomarkers and for the detection of complications." (PMID 38353727, 2024). "It soon became clear that, in juvenile diabetes (now called type 1 diabetes), circulating insulin levels were low owing to autoimmune destruction of the pancreatic β cells." (PMID 38299589, 2024). "Type 1 diabetes (T1D) is an autoimmune disease characterized by the attack of T cells on pancreatic β cells, which are responsible for insulin production and the regulation of blood glucose levels." (PMID 38322269, 2024). "In two crossover euglycemic insulin clamp trials, 21 young patients with type 1 diabetes for >1 year received 30 g of carbohydrates and, alternatively, a low-protein or high-protein meal and a low-protein/low-fat or high-protein/high-fat meal." (PMID 39519472, 2024). "Type 1 diabetes (T1D) is an autoimmune condition characterized by the destruction of insulin-producing beta cells within the islets of Langerhans in the endocrine pancreas." (PMID 38540105, 2024). "Although it's commonly believed that individuals who exhibit symptoms of diabetic ketoacidosis (DKA) have type 1 diabetes and need to take insulin continuously for the rest of their lives, this isn't always the case." (PMID 39634998, 2024). "In patients with type 1 diabetes, insulin treatment should be prioritised, as any discontinuation in its supply can lead to life-threatening diabetic ketoacidosis." (PMID 39063405, 2024). "In a randomized, three-period cross-over study, twelve adults with insulin-pump-treated type 1 diabetes followed an HC (energy provided by carbohydrate: 48%, fat: 33%, protein: 19%), HF (19%, 62%, 19%), and an HP (19%, 57%, 24%) diet for one week." (PMID 38257092, 2024). "Recent studies have shown improved insulin adherence through a reduction in the number of missed bolus doses, better mealtime dosing, and increased TIR in people with type 1 diabetes using smart insulin pens with connectivity in a real-world setting." (PMID 39791645, 2024). "A key CD4+ T cell epitope identified in type 1 diabetes is insulin B chain amino acids 9–23 (InsB9–23)." (PMID 38097717, 2024). "Context: Type 1 diabetes (T1D) results from the autoimmune T-cell mediated destruction of pancreatic beta cells leading to insufficient insulin secretion." (PMID 38397298, 2024). "Nevertheless, this study is meaningful in that it confirmed adverse effects and changes in insulin administered for blood glucose control after SGLT2 inhibitor administration in dogs with naturally occurring type 1 diabetes." (PMID 38686463, 2024).
type 1 diabetes (continued). "In cases of Type 1 diabetes, where the pancreas cannot produce sufficient insulin, patients require insulin injections." (PMID 39363915, 2024). "Use of Continuous Subcutaneous Insulin Infusion (CSII) has been shown to improve glycemic outcomes in Type 1 Diabetes (T1D), but high costs limit accessibility." (PMID 39090697, 2024). "The expression of hepatic CYP8B1 is regulated exactly as HSDL2: It is (i) increased upon fasting, (ii) activated by PPARα agonists, (iii) repressed by insulin, and (iv) elevated in type 1 diabetes." (PMID 38820148, 2024). "Plasma insulin levels were numerically higher in the type 1 diabetes group compared with the healthy participants." (PMID 38427076, 2024). "Acute hypoglycemic episodes are less common in T2DM than in type 1 diabetes, but they can occur if insulin or sulphonylurea medications are used." (PMID 38467963, 2024). "In type 1 diabetes disease, the immune system of the patient attacks and destroys beta cells which are insulin-producing." (PMID 38355744, 2024). "Type 1 diabetes (T1DM) is an autoimmune disorder caused by the destruction of B cells and deficiency of insulin." (PMID 39062227, 2024). "In a zebrafish embryo model of type 1 diabetes, where the majority of the insulin-producing cells were killed, the researchers also evaluated the nanorods." (PMID 39771551, 2024). "Prior to insulin’s introduction in 1922, the prognosis for individuals living with Type 1 diabetes was dire." (PMID 39691108, 2024). "Many formulae estimating glucose disposal rate in type 1 diabetes infer insulin sensitivity from clinical data." (PMID 38702680, 2024). "This narrative review assesses the use of automated insulin delivery (AID) systems in managing persons with type 1 diabetes (PWD) in the pediatric population." (PMID 38785359, 2024). "We did not observe this phenomenon, possibly because our volunteers with type 1 diabetes arrived fasted, maintaining only basal exogenous insulin delivery." (PMID 38662134, 2024). "Insulin treatment for type 1 diabetes was present in 1% of women with TS and 1% in control women (NS)." (PMID 37758506, 2024). "Access to affordable healthcare and treatment, including insulin use, is crucial for the survival of individuals with type 1 diabetes (T1D)." (PMID 38304693, 2024). "Islet autoantibodies are markers found in the blood when insulin-producing cells in the pancreas become damaged and can be used to predict future development of type 1 diabetes." (PMID 38582818, 2024). "Type 1 diabetes is a demanding chronic condition that requires diligent blood glucose monitoring and timely insulin administration by patients who must integrate self-management into their daily lives." (PMID 39509700, 2024). "Children with type 1 diabetes require lifelong insulin treatment and self-management; therefore, there is an urgent need for the active development and use of mobile apps for young patients with type 1 diabetes." (PMID 38338253, 2024). "It is clear that IGF-I insufficiency is common in type 1 diabetes, and as a result of this decrease, the sensitivity of cells to insulin decreases." (PMID 38468961, 2024). "Type 1 diabetes mellitus (T1DM) is an autoimmune condition which is characterised by the destruction of pancreatic insulin-producing β-cells, leading to hyperglycaemia." (PMID 39037470, 2024). "In type 1 diabetes, it is well-known that the patients, usually teenagers or young adults sometimes deliberately omit insulin to lose weight, or restrict their eating, or alternate between vomiting and binge eating." (PMID 38198020, 2024). "Type 1 diabetes is an autoimmune disease that usually develops in childhood or adolescence and results in insufficient insulin production." (PMID 39650520, 2024). "This study investigates impaired awareness of hypoglycaemia (IAH), a complication of insulin therapy affecting 20–40% of individuals with type 1 diabetes." (PMID 38396205, 2024).